LEPR (leptin receptor)
Diseases named in the same sentence as LEPR in open-access papers (continued):
Sharing a sentence is not in itself a finding about the gene and the disease.
asthma (continued). "Moreover, a sex- and genotype-stratified analysis of the IOW data indicated that acetaminophen was associated with asthma to a similar extent among males and females carrying two common alleles of LEPR polymorphisms." (PMID 30231898, 2018). "To analyze if genotypes of LEP and LEPR polymorphisms together with their serum levels could be good predictors of asthma risk, we included them in the stepwise logistic regression analysis." (PMID 30203371, 2018). "In contrast, among those carrying at least one copy of the minor allele of LEPR polymorphisms, the magnitude of association between acetaminophen use and asthma was pronounced among males (aPR = 6.83, 95% CI: 2.87–16.24), but not among females (aPR = 1.22, 95% CI: 0.61–2.45)." (PMID 30231898, 2018). "We are still looking into the part that the leptin receptor gene Gln223Arg plays in the development of asthma and how it affects controlling symptoms." (PMID 40361972, 2025). "Research data suggest that leptin/leptin receptor system expression and signaling is altered in the airways of patients with asthma and COPD." (PMID 21040518, 2010). "In analysis of the IOW cohort, we explored whether the identified sex-related effect modification of the acetaminophen-asthma association varied across LEP and LEPR genotypes." (PMID 30231898, 2018). "Two analyzed LEPR polymorphisms (K109R and Q223R) did not affect significantly serum leptin receptor level independent of asthma status (P = 0.693 and P = 0.692, respectively)." (PMID 30203371, 2018). "This investigation sought to determine whether sex modifies the acetaminophen-asthma association and whether leptin (LEP) and leptin receptor (LEPR) gene polymorphisms modulate the sex-specific associations." (PMID 30231898, 2018). "Association of this variant with leptin serum level and lack of association between leptin receptor and its level in asthma were not published previously." (PMID 30203371, 2018). "To our knowledge, no other association studies of LEPR polymorphisms were performed in asthma so far, so we cannot compare our results." (PMID 30203371, 2018). "Peripherally, the magnitude of leptin receptor expression in visceral fat has been related to BHR, which has led to the concept that obesity-asthma is potentially a disease of peripheral adipose tissues." (PMID 27965756, 2015). "The leptin receptor is expressed in NCI-H292 cells and airway epithelial cells in asthma." (PMID 34074279, 2021). "In our previous study, we reported that childhood asthma is associated with polymorphism in leptin gene (LEP), but not with LEPR." (PMID 30203371, 2018).
breast tumor (10 papers, 2007 to 2024). "Multivariable-adjusted associations of body fatness measures with LEPR protein expression in breast tumor tissues, stratified by menopausal status." (PMID 35846306, 2022). "Multivariable-adjusted associations of body fatness measures with LEPR protein and LEPR gene expression in breast tumor tissues." (PMID 35846306, 2022). "Multivariable-adjusted associations of body fatness measures with LEPR protein expression in breast tumor tissues, stratified by ER status." (PMID 35846306, 2022). "Multivariable-adjusted associations of body fatness measures with LEPR protein expression in breast tumor tissues, stratified by race." (PMID 35846306, 2022). "Overexpression of leptin and leptin receptor in breast tumors and its association with tumor aggressiveness suggest that leptin can also influence breast tumor growth and progression via an autocrine pathway." (PMID 26359358, 2015). "LEPR is highly expressed in breast tumour tissue and has six splice variants encoding four isoforms that share an identical intracellular domain Box1 that is critical for Janus kinase (JAK) binding and activation." (PMID 25482303, 2014). "Our data show for the first time a strong correlation between SK1 and LEPR expression in human primary breast tumours and associated lymph node metastases." (PMID 25482303, 2014). "Our findings suggest that measures of body fatness are associated with the expression of adipokine receptors – primarily LEP and LEPR – in breast tumors." (PMID 35846306, 2022). "Immunohistochemical analysis of breast tumors, peritumoral and adjacent normal breast tissues show elevated expression of leptin receptor and leptin in 83 and 92% of breast tumors, respectively, while adjacent normal breast tissue exhibit weak positivity." (PMID 34389732, 2021). "We demonstrated that both LepR mRNA and FGFR1 mRNA were both positively associated with Jak2 mRNA in primary breast tumors." (PMID 33019728, 2020). "Variation in LEPR IHC expression was observed by breast tumor clinicopathologic features, while the expression of LEP, ADIPOQ, ADIPOR1, and ADIPOR2 did not appear to vary by tumor clinicopathology." (PMID 32046756, 2020). "Subgroup analysis of the multivariate associations of LEP, LEPR, ADIPOQ, ADIPOR1, and ADIPOR2 IHC expression with breast tumor clinicopathologic features among Black women yielded similar findings." (PMID 32046756, 2020). "The novelty of our findings disclose leptin/leptin receptor signaling as one of the main adipose-derived microenvironmental mediators that deeply affects breast tumor biology." (PMID 32727138, 2020). "Additional studies are needed to clarify the clinical implications of LEPR expression and the mechanisms involved in the regulation of LEPR expression, to ultimately determine the utility of this biomarker in understanding breast tumor aggressiveness." (PMID 32046756, 2020). "Our findings show for the first time that human primary breast tumours and associated lymph node metastases exhibit a strong correlation between SK1 and leptin receptor expression (Pearson R = 0.78 and R = 0.77, respectively, P <0.001)." (PMID 25482303, 2014). "Herein, we demonstrate a relationship between FGFR1, leptin, and LepR in human breast tumors." (PMID 33019728, 2020). "In summary, findings from this study suggest that lower LEPR IHC expression within the breast tumor microenvironment might serve as an indicator of increased breast tumor aggressiveness." (PMID 32046756, 2020). "While the studies herein do not fully elucidate these complexities, they provide relationship data on two receptors in breast tumors that may be influenced by excess adipose tissue and drive tumor progression, LepR and FGFR1." (PMID 33019728, 2020). "Although as indicated leptin and leptin receptor expression have been identified in human breast tumors, proteins associated with leptin signaling have not been characterized." (PMID 18162139, 2007).
breast tumor (continued). "In the current study, we hypothesize that measures of body fatness are associated with LEPR, ADIPOR1, and ADIPOR2 expression profiles in the breast tumor microenvironment, which might contribute mechanistically to the development of more aggressive breast tumor phenotypes and poorer prognosis." (PMID 35846306, 2022). "Building on our prior research, here we examined the associations of body fatness measures with protein and gene expression of the adipokines, LEP and ADIPOQ, and the adipokine receptors, LEPR, ADIPOR1, and ADIPOR2 in breast tumor tissues." (PMID 35846306, 2022). "In conclusion, we define a positive relationship between leptin, LepR and FGFR1 in primary human breast tumors and a positive relationship between LepR and FGFR1 in the tissue adjacent to tumors." (PMID 33019728, 2020). "Analysis of clinical samples showed overexpression of leptin receptor in 83% of breast tumor samples whereas no expression of leptin receptor was observed in normal mammary epithelial cells." (PMID 26359358, 2015).
hepatocellular carcinoma (10 papers, 2015 to 2024). A malignant tumor that arises from hepatocytes. "The clinical association of leptin and leptin receptor expression with cancer patient outcomes has been explored, and the positive association of leptin with hepatocellular carcinoma risk was recently reported." (PMID 33799880, 2021). "Overexpression of leptin receptor was significantly associated to the unfavored TNM status in hepatocellular carcinoma." (PMID 33799880, 2021). "In another report of human hepatocellular carcinoma, leptin/leptin receptor expression was observed in both tumor and endothelial cells, in parallel to the degree of angiogenesis." (PMID 33799880, 2021). "This represents the first study reporting that LEPR promoted proliferation, migration, and invasion and inhibited apoptosis in hepatocellular carcinoma by regulating ANXA7." (PMID 33397392, 2021). "We performed bioinformatics analysis, qRT-PCR, western blotting, immunohistochemistry, immunofluorescence, enzyme-linked immunosorbent, coimmunoprecipitation assays and a series of functional assays to investigate the roles of LEPR in hepatocellular carcinoma." (PMID 33397392, 2021). "This occurred despite previous use of these antibodies to specifically detect leptin and leptin-receptor in the hepatocellular carcinoma, breast, biliary tract, appendix and stomach." (PMID 29615085, 2018). "In human hepatocellular carcinoma, leptin/leptin receptor expressions were detected in both tumor and endothelial cells in parallel with the degree of angiogenesis." (PMID 29682217, 2018). "Although the majority of the mutated genes detected in cirrhotic tissues were thought to be passenger mutations, the leptin receptor gene (LEPR) was identified as a putative cancer-related gene mutated in both cirrhotic tissues and hepatocellular carcinoma." (PMID 26083936, 2015). "LEPR could enhance proliferation, migration, and invasion and inhibit apoptosis in lymphatic metastasis of hepatocellular carcinoma by directly interacting with ANXA7." (PMID 33799880, 2021). "In this study, we explored whether LEPR promotes proliferation, migration, and invasion and inhibits apoptosis in hepatocellular carcinoma by regulating ANXA7." (PMID 33397392, 2021). "In the mouse, leptin the “satiety” hormone and leptin receptor are essential for expression of ApoM, but excess concentrations of leptin inhibited ApoM mRNA expression in a dose-dependent manner in the human hepatoma cell line HepG2, suggesting that leptin may mediate ApoM expression." (PMID 35945490, 2022). "The relationship of leptin (LEP) and polymorphism of leptin receptor (LEPR) were studied in patients with hepatocellular carcinoma (HCC) and compared with those with liver cirrhosis to find out the extent of the risk of LEPR on patients with HCC." (PMID 33369452, 2020). "Diffuse granular cytoplasmic expression of leptin-receptor in non-neoplastic hepatocytes (left), and weak focal (f) or strong diffuse (g) staining of leptin-receptor in hepatocellular carcinoma cells (right)." (PMID 29615085, 2018).
melanoma (10 papers, 2014 to 2025). A malignant, usually aggressive tumor composed of atypical, neoplastic melanocytes. "In this study, grafted B16 melanoma grew faster in obese mice, but those with LepR deficient T cells were better able to control tumor growth, associated with reduced PD-1 expression on CD8+ T cells." (PMID 33927722, 2021). "Three neuronal-related genes (PCLO, PLXNA4, and EPHA7), and the gene encoding the leptin receptor (LEPR), all reported as mutated in melanoma at a variable frequency (37%, 11%, 16% and 8% of samples in TCGA cohort, respectively), were altered more frequently in R compared to NR patients." (PMID 37739939, 2023). "In one study, melanoma-infiltrating CD8+ T cells were found to exhibit higher LepR levels than cells present in lymphoid tissue, and tumors engineered to express leptin grew more slowly, leading to improved survival." (PMID 33927722, 2021). "This adipokine acts in an autocrine manner on melanoma cells which express both ObR (leptin receptor) and leptin." (PMID 34068679, 2021). "The serum levels of leptin receptor decreased gradually with the stage of melanoma, being highest at in situ and lowest at stage IV." (PMID 31936623, 2020). "In summary, we demonstrated the anti-cancer effect of a neutralizing nanobody targeting LepR in a mouse model of melanoma." (PMID 24587106, 2014). "In this study we assessed the effects of a neutralizing anti-LepR nanobody in a mouse model of melanoma." (PMID 24587106, 2014). "Leptin could bind to the leptin receptor (OB-R), and then contributes to the drug resistance in melanoma cells via activating the PI3K/AKT and MEK/ERK signaling." (PMID 34095111, 2021). "However, future studies investigating leptin signaling in lymphocytes by using leptin receptor knockout mice will be important to evidence this relationship in melanoma models." (PMID 31528182, 2019). "We next tested the efficacy of nanobody targeting LepR in the established melanoma model." (PMID 24587106, 2014). "In an in vitro experiment, the expression of LepR in B16 melanoma cells was confirmed by RT-PCR." (PMID 24587106, 2014). "In this study we assessed the effect of a leptin receptor antagonist on melanoma progression." (PMID 24587106, 2014). "The rates of decreased serum leptin receptor concentrations under the cut-off value were higher than those of increased serum 5SCD levels in patients with in situ, stage III and stage IV melanomas and in all melanoma patients." (PMID 31936623, 2020). "Additionally, to verify the involvement of leptin in modulating the response of melanoma cells to DTIC therapy, B16F10 cells were cultured in the medium containing serum of genetically obese mice strains ob/ob (leptin deficient) or db/db (leptin receptor deficient)." (PMID 29568521, 2018).
steatosis (10 papers, 2012 to 2024). Increased lipid within the cytoplasm of cells. "Loss of Slc39a5 improves liver function and steatosis in leptin-receptor deficient female mice and in female mice challenged with high-fat high fructose diet (HFFD)." (PMID 39671241, 2024). "ZDF rats constitute a genetically modified T2D model, in which leptin receptor deficiency and genetic defects of β-cells converge to induce severe T2D accompanied by its common comorbidities, such as fatty liver and steatosis." (PMID 34555055, 2021). "When leptin receptor-deficient, the body loses protection against lipotoxicity, steroid regulatory element binding protein gene expression is upregulated, free fatty acids accumulate in the liver, and hepatocellular steatosis occurs." (PMID 39767635, 2024). "Serum leptin levels are increased in both patients with NAFLD and in animal models of the disease and may be associated with the development of hepatocyte steatosis and its progression through OB-R (leptin receptor) activation of the PI3-K/Akt kinase pathway." (PMID 35405942, 2022). "Much evidence indicates that LEPR serves as a novel biomarker for leptin sensitivity, and the augmentation of LEPR is related to the reduction of steatosis." (PMID 37727633, 2023). "Genetic deficient ob/ob (leptin deficient), db/db mice (leptin-receptor defective) or Zucker rats (leptin-receptor deficient), do not develop steatosis implicitly, unless fed an MCD or an HFC diet." (PMID 29847555, 2018).
type 1 diabetes (10 papers, 2015 to 2025). "However, this is in fact in line with some previous studies, illustrating the contrast between our model and those of e.g., leptin receptor deficiency (i.e., db/db mice) and type 1 diabetes (e.g., streptozotocin treatment)." (PMID 31379826, 2019). "Among these models, streptozotocin (STZ)-induced cardiomyopathy of type 1 diabetes mellitus (T1DM) and leptin receptor deficient (db/db)- or leptin deficient (ob/ob)-cardiomyopathy of T2DM are frequently used in the study of lncRNAs." (PMID 30342478, 2018).
Cognitive impairment (9 papers, 2017 to 2023). Abnormal cognition is characterized by deficits in thinking, reasoning, or remembering. "We found that LepR deficiency would protect mice from the CCH-induced cognitive impairment and WMLs by inhibiting glial activation and suppressing proinflammatory cytokine expression as well as promoting anti-inflammatory cytokine expression in the white matter." (PMID 33380900, 2020). "This was also supported by other recent observations showing that low levels of leptin, leptin resistance, or leptin receptor deficiency in the hippocampus of diabetic rodents may be involved in cognitive deficits." (PMID 28621759, 2017). "Meanwhile, low and high doses of Zn supplementation increased LepR expression in obese rats, suggesting that both doses of Zn treatment can modulate LepR expression in hippocampus and effectively ameliorate cognitive impairments." (PMID 36977735, 2023). "These regions express the long form of leptin receptor LepRb, which is the unique leptin receptor capable of transmitting complete leptin signaling, and are the first regions to be affected by chronic neurocognitive deficits, such as mild cognitive impairment (MCI) and Alzheimer’s Disease (AD)." (PMID 35563589, 2022). "Here, we also document the high incidence of delay in learning ability, possibly due to intellectual impairment, and aggressive behavior in children with LEP or LEPR deficiency that appear to be milder or absent in children with MC4R deficiency." (PMID 37659411, 2023). "Mice that do not express the leptin receptor (db/db) exhibit cognitive deficits, and obese rodents, which are insensitive to leptin, also show cognitive deficits and have deteriorated LTP." (PMID 34539357, 2021).
hypogonadism (9 papers, 2010 to 2025). A disorder characterized by decreased function of the gonads. "Patients with LEPR variants may present with hypogonadism and failure to enter/complete puberty." (PMID 40528426, 2025). "Additionally, a mutation in the leptin receptor also caused hypogonadism in humans." (PMID 32411228, 2020). "No hypogonadism was observed in five LEPR wt/- from this family, while in three out of five related subjects who were -/- for this variant, hypogonadism was observed." (PMID 34448070, 2021).
lung cancer (9 papers, 2011 to 2024). A malignant neoplasm involving the lung. "In addition, the presence of polymorphism LEPR is known to show a statistically significant difference between lung cancer patients and controls (p=0.007)." (PMID 36909892, 2023). "LEPR gene polymorphisms are linked to lung function decline in COPD, and NSUN3 is associated with lung cancer development in COPD." (PMID 39143598, 2024).
polycystic ovary syndrome (9 papers, 2015 to 2025). A disorder that manifests as multiple cysts on the ovaries. "For many years, leptin/LepR-deficient mice, such as db/db mice, have been used as animal model to study polycystic ovary syndrome (PCOS), which is widely acknowledged as the most frequent female endocrine disorder, with a variety of etiological factors and clinic manifestations." (PMID 26529315, 2015). "Studies also proposed a relationship between the leptin receptor and PPARγ in the pathogenesis of polycystic ovary." (PMID 41275450, 2025). "Because high testosterone and LH levels are hallmarks of polycystic ovary syndrome (PCOS), we assessed if AR in LepR neurons plays a role in the neuroendocrine dysregulation of hyperandrogenemia-induced PCOS-like phenotype in mice." (PMID 40276575, 2025).